VWF (von Willebrand factor)
Diseases named in the same sentence as VWF in open-access papers (continued):
Sharing a sentence is not in itself a finding about the gene and the disease.
hypercoagulability (117 papers, 2007 to 2026). "It has been established that the SARS-CoV-2 induces chronic oxidative stress at the endothelial level, causing the release of von Willebrand factor multimers and hypercoagulability." (PMID 41585277, 2025). "Second, SARS-CoV-2 infection is associated with a hypercoagulable state, characterized by elevated levels of fibrinogen, von Willebrand factor, and platelet activation." (PMID 41464184, 2025). "Studies suggest that the imbalance between ADAMTS13 and VWF is associated with angiogenesis and hypercoagulability and that this is important for cancer prognosis." (PMID 40699668, 2025). "Known hereditary thrombophilia and vWF promoter polymorphism haplotype 1 are used as criteria to decide the starting of thromboprophylaxis in patients with CS by 30% and 13% of centers, respectively." (PMID 38529392, 2024). "Proteomics: Age-related shifts in protein profiles, including increased levels of the fibrinogen, factor VIII, and von Willebrand factor, are linked to hypercoagulability." (PMID 39857599, 2024). "ADAMTS-13 and vWF are associated with the severity of LC via hypercoagulability, which represents a significant risk factor for PVT development." (PMID 38473925, 2024). "While cytokines, von Willebrand factor, and fibrinogen are responsible for increased thrombotic factors, they also cause a state of hypercoagulability due to the increased number of plasma components." (PMID 38255892, 2024). "Changes in prothrombotic factors like fibrinogen, D-dimer, factor VIII, and von Willebrand factor are responsible for the hypercoagulability associated with COVID-19." (PMID 37090373, 2023). "For example, cirrhotic patients frequently have hypercoagulability which is associated with elevated VWF and results in markedly increased risk for thromboembolism." (PMID 37950277, 2023). "Thrombophilia associated with vWF, FVIII, and FV is the result of an impaired turnover of these proteins, which favors the factors’ synthesis, due to an alteration in natural inactivators, such as ADAMTS13 for vWF and APC and PS for FVIII and FV, respectively." (PMID 35955419, 2022). "Based on our results, we believe that the imbalance between ADAMTS13 enzyme and VWF substrate is directly associated with the pathophysiology of LC via hypercoagulability, and that Et-induced LC progression was also directly involved in liver injury." (PMID 35407443, 2022). "In summary, the results of our study indicate that ADAMTS13: AC, VWF: Ag, and Et are interrelated and associated with the severity of LC via hypercoagulability." (PMID 35407443, 2022). "Kynurenine is positively associated with vWF and with prothrombin fragments F(1+2), reflecting hypercoagulability in CKD patients." (PMID 30322010, 2018). "In this study we show for the first time an in vivo association between hypercoagulability and an increased vWF antigen to ADAMTS13 ratio, platelet aggregates in intrahepatic portal vessels and decline in natural anticoagulants." (PMID 28839178, 2017). "In subclinical hypothyroidism, hypercoagulation is caused by increased plasma concentrations of fibrinogen, vWf, factor VII, factor X and plasminogen activator inhibitor-1." (PMID 24507241, 2014). "Known hereditary thrombophilia (e.g. factor V Leiden/Prothrombin 2021a), and vWF promoter polymorphism haplotype 1 were reported to be used in the decision to start thromboprophylaxis by seven, and three centers, respectively, while non-0 blood group (BG) was not considered by any center." (PMID 35505430, 2022). "In conclusion, ADAMTS13, VWF, and Et may be interrelated and associated with the severity of LC via hypercoagulability." (PMID 35407443, 2022). "Hormonal status also matters: pregnancy increases fibrinogen, FVIII, vWF, and lowers protein-S activity; combined oral contraceptives shift the profile toward hypercoagulability." (PMID 41439002, 2025).
hypercoagulability (continued). "Investigations revealed a hypercoagulable state due to hyperactive Von Willebrand factor, prompting treatment adjustments that resulted in gradual improvement of the thrombosis." (PMID 40129850, 2025). "It is established that high VEGF-A levels can result in a hypercoagulable state by increasing the expression of tissue factor and the release of von Willebrand factor in endothelial cells." (PMID 40075026, 2025). "An imbalance in the VWF antigen (VWF:Ag)/ADAMTS13 activity (ADAMTS13:AC) ratio was reported to be associated with angiogenesis and hypercoagulability as well as prognosis in patients with various types of cancer, especially those receiving chemotherapy." (PMID 40699668, 2025). "Elevated fibrinogen, factor VIII, and von Willebrand factor levels promote a hypercoagulable state, while cytokines like IL-6 and TNF-α drive persistent inflammation." (PMID 41181439, 2025). "The main risk factors for CKD are insulin resistance and hypercoagulability (high fibrinogen, factor VII, and von Willebrand factor levels)." (PMID 36793875, 2023). "We captured a rise in plasma vWF prior to exacerbation, for the first time showing that endothelial-related hypercoagulability increases already before clinically evident decompensation." (PMID 35181700, 2022). "Older age was associated with a progressive shift of the coagulation balance towards hypercoagulability, as detected by higher vWF and F8 levels and lower PC levels, resulting in a strong impact on F8/PC ratio." (PMID 36313186, 2022). "The pathophysiological mechanism of hypercoagulability among patients with Graves’ disease is associated with the elevation of plasminogen activator inhibitor (PAI-1) and vWF." (PMID 35698703, 2022). "Patients with NAFLD have insulin resistance and hypercoagulability (high fibrinogen, factor VII, and von Willebrand factor levels), which are risk factors for CKD." (PMID 34211614, 2021). "How elements such as factor VIII, antithrombin, von Willebrand factor, and others explain the observed hypercoagulability has yet to be fully elucidated." (PMID 33641491, 2021). "A hypercoagulable state was observed in both the patients with a high level of VWF and VWF:RCo, D-dimer, and coagulation Factor VIII." (PMID 34341358, 2021). "The indicators of hypercoagulable state like the activity of the Von Willebrand factor, levels of Factor VIII, and D dimer are lower in patients on treatment." (PMID 32704356, 2020). "Patients with severe COVID-19 infection often have laboratory findings consistent with a hypercoagulable state suggesting widespread thrombosis and fibrinolysis as well as elevated levels of D-dimer, Von Willebrand factor (VWF), and Factor VIII." (PMID 33312811, 2020). "Increased levels of tissue factor, tissue plasminogen activator, plasminogen activator inhibitor-1, and von Willebrand factor which all contribute to hypercoagulability are reported to be found proximately after surgical stimulus." (PMID 30885139, 2019). "These abnormalities are in favor of a hypercoagulable state, with enhanced levels of vWF, fibrinogen, thrombin, factor VII, TF, and PAI-1, as well as reduced antithrombin activity." (PMID 30322010, 2018). "Sodium levels in the range of 145–150 mM have been reported to induce secretion of von Willebrand Factor by endothelial cells leading to hypercoagulability and thrombosis." (PMID 28878383, 2017). "Nevertheless, pregnancy is a hypercoagulation state with very high levels of VWF and UL-VWF released from endothelial cells and the placenta, and can trigger TTP (acquired or congenital), aHUS, or other TMAs." (PMID 25386342, 2014). "A critical factor in thrombophilia assessment is the FVIII/vWF ratio." (PMID 40429442, 2025). "Furthermore, simvastatin has shown a greater capacity to reduce von Willebrand factor (vWF) levels, underscoring its crucial role in managing SCD-associated hypercoagulability." (PMID 41409427, 2025).
hypercoagulability (continued). "VWF is also very prone to changes in that it may be elevated at one stage in a coagulopathic disease’s progression, but hypercoagulability can deplete it rapidly, even thereby leading to hypocoagulability." (PMID 39942772, 2025). "HGWD prolonged APTT, TT, and PT appropriately and ameliorated the blood hypercoagulability of OVX rats, which might be associated with reduced plasma vWF levels and inhibition of platelet adhesion and aggregation." (PMID 40757856, 2025). "The resulting direct invasion of endothelial cells, coupled with an increase in cytokines, acute phase reactants, and prothrombotic factors like von Willebrand factor (vWF), factor VIII, D-dimer, fibrinogen, etc. causes endothelial injury and subsequent thrombophilia." (PMID 37090373, 2023). "Additionally, desmopressin administration induced the release of Von Willebrand factor multimers, which aggravated thrombophilia." (PMID 38001743, 2023). "vWF is likely one of the key components of hypercoagulability in cirrhosis." (PMID 37685826, 2023). "Other contributing factors are acquired hypercoagulability through elevated levels of prohemostatic von Willebrand factor (vWF) and decreased levels of the naturally occurring anticoagulants protein C, protein S, and antithrombin as well as heparin cofactor II." (PMID 38994395, 2022). "VWF is a well-known molecule in vascular (endothelial) injury, platelet-platelet adhesion and is generally involved in hypercoagulation, if found to be increased which could contribute to coagulopathies seen in patients with long COVID." (PMID 36131342, 2022). "Thus, PTSD caused hypercoagulation associated with increased concentrations of factor VIII, von Willebrand factor, and fibrinogen and with platelet aggregation." (PMID 36499055, 2022). "Monoclonal-antibody-based anti-vWF immunotherapy (caplacizumab) is used in the context of severe thrombophilia, regardless of the cause of the disorder." (PMID 35955419, 2022). "Although a hypercoagulable state caused by hyperthyroidism could not be established by the criteria chosen, increases in plasma fibrinogen and vWF : Ag concentrations in the hyperthyroid group were consistent with hypercoagulability." (PMID 34590754, 2021). "Our results suggested that acrolein induces hypercoagulability partly through the secretion of VWF." (PMID 33939120, 2021). "Our results showed that acrolein may contribute to an early hypercoagulable state after TBI by regulating VWF secretion." (PMID 33939120, 2021). "In this case-control study, we analyzed clinical characteristics and genetic thrombophilia markers (factor V Leiden (FVL), prothrombin G20210A (FIIV), Tyr2561 variant of von Willebrand factor (VWF-V)) in 42 patients with AF and LA thrombus (LAT) and in 68 control patients with AF without LAT (CTR)." (PMID 34184557, 2021). "However, we argue here that detailed measurement of levels of fibrin(ogen), D-dimer and other markers of hypercoagulation, especially P-selectin and VWF, are of importance during thromboprophylaxis." (PMID 32708334, 2020). "First, excessively secreted catecholamines may increase the levels of factor VIII and VWF antigen and activate platelets, resulting in hypercoagulability." (PMID 32256452, 2020). "It is not known whether there is a direct clinical relevance of HF stage-specific hypercoagulability followed by attenuated vWF secretion as shown in this mouse model." (PMID 26565707, 2015). "Our research group have previously studied these hemostatic markers in the same group of patients before renal transplantation and showed that the imbalance between ADAMTS13 and VWF levels may contribute to the hypercoagulability state." (PMID 26229221, 2015). "Collectively,these studies highlight that CS itself, independent of treatment, predisposespatients to a hypercoagulable state, likely due to increased levels ofprocoagulant factors such as von Willebrand factor (vWF) and factor VIII, aswell as impaired fibrinolysis." (PMID 41313192, 2025).
hypercoagulability (continued). "Surge of procoagulants may be secondary to the release of the von Willebrand factor (vWF) from an injured endothelium or from hypoxia-mediated hypercoagulability producing an imbalance of the physiologic anticoagulant-procoagulant homeostasis leading to a hypercoagulable state." (PMID 41541110, 2023). "Moreover, the imbalance between ADAMTS13 enzyme and VWF substrate also reflects hypercoagulability." (PMID 35407443, 2022). "However, other retrospective studies and case reports have shown that these patients have unusually high levels of plasma VWF, suggesting that the hypercoagulability observed may be dependent on intravascular thrombosis." (PMID 32881285, 2020). "Tissue factor-activated TEG, although typically insensitive to hypercoagulation compared to PT and aPTT, may be capturing the effects of vWF on platelet activation-stimulated cell-driven coagulation, which can be detected by whole blood-based, but not plasma-based, clot assays." (PMID 25546432, 2014). "The concurrent shortening of APTT provides clear evidence of hypercoagulability through the intrinsic pathway, likely mediated by elevated levels of procoagulant factors such as factor VIII and von Willebrand factor, which are well documented in T2DM." (PMID 41563951, 2026). "Increasing fibrinogen levels, von Willebrand factor, clotting factors (VII, VIII, IX, X, XII) and reduction in fibrinolytic activity lead to a controlled hypercoagulable state." (PMID 40781663, 2025). "We found that VWF, identified from the WCLEV proteome, is up-regulated in patients, consistent with the hypercoagulability in patients of OAPS." (PMID 38225453, 2024). "Chronic HIV infection is characterized by both abnormal immune activation and hypercoagulability, manifested by increased expression of CVD biomarkers such as interleukin 6, C-reactive protein, D-dimer, and Von-Willebrand’s factor (vWF)." (PMID 35215140, 2022). "In a previous study, we have described the association between VWF, ADAMTS13, and D-Dimer with different levels of renal dysfunction in DM1 patients and we have raised the hypothesis that inflammation could be associated with hypercoagulability in patients with diabetic nephropathy." (PMID 26770985, 2016). "Since then, a number of studies reported on hypercoagulability in endogenous hypercortisolism, the most consistent alterations being an increase in clotting factors, in particular factor VIII and von Willebrand factor (vWF), enhanced thrombin generation and reduced fibrinolysis." (PMID 39352631, 2025). "Another physiological adaptation during pregnancy and the peripartum period is a hypercoagulable state, which leads to increased levels of thrombotic factors such as VII, VIII, X, XII, von Willebrand factor, and fibrinogen and reduced levels of protein S and fibrinolysis." (PMID 37046556, 2023). "The non-O BT is associated with increased von Willebrand factor (vWF) and increased factor VIII levels, which cause thrombophilia." (PMID 36983111, 2023). "In brief, TTP is a hypercoagulable state, caused by inhibition of ADAMTS-13, a factor-cleaving protease, by auto-antibodies which leads to a lack of degradation of von Willebrand factor multimers." (PMID 30073173, 2018). "Atrial fibrillation results in hypercoagulability, and in addition, non-O blood group antigens may enhance von Willebrand factor expression, leading to inflammatory changes and structural remodeling of atrial muscle." (PMID 38586426, 2024). "Another ED-related factor contributing to hypercoagulability in cirrhosis is the significantly increased production of endothelium liver-independent coagulation or anticoagulation factors such as Factor (F) FVIII, von Willebrand factor (vWF), and plasminogen activator inhibitor 1 (PAI-1)." (PMID 37685826, 2023).
hypercoagulability (continued). "However, higher concentrations of von-Willebrand factor (vWf) and Factor VIII as well as lower concentrations of anticoagulant factors including Protein C and S have also been reported in CHC infection suggesting hypercoagulability." (PMID 28481325, 2017).
diabetes (116 papers, 2008 to 2026). "For instance, a prior study reported an association between elevated ADAMTS13 activity (which cleaves VWF multimers and reduces their functional activity) and increased diabetes risk." (PMID 40969184, 2025). "Glucose control, as reflected by HbA1c, glucose levels, and diabetes diagnosis, was independently associated with higher vWF, resulting in a parallel increase in F8 and F8/PC ratio, the latter more evident in the presence of diabetes." (PMID 36313186, 2022). "Elevated vWF plasma levels have been described in diseases associated with systemic inflammation, such as chronic kidney disease, diabetes, and sepsis." (PMID 33920144, 2021). "In the ASCET study, age, smoking, and diabetes mellitus were associated with elevated vWF in plasma." (PMID 33096906, 2020). "Multiple linear regression analysis revealed that elderly age, the presence of diabetes mellitus, and vWF levels were independently associated with low BDNF levels in stable CAD patients." (PMID 29409455, 2018). "Diabetes causes a high risk of platelet aggregation and increases release of von Willebrand factor, which promotes the platelet aggregation and results in damaging to endothelial cells in blood vessels." (PMID 29724122, 2018). "In our study, ADAMTS13 activity was associated with an increased risk of incident diabetes, even after adjustment for other known risk factors, including VWF antigen, fasting glucose and fasting insulin levels." (PMID 27787621, 2017). "Increased VWF antigen level was associated with a 12% (HR 1.12 [95% CI 1.03, 1.21]) increased risk of incident diabetes per SD in the age- and sex-adjusted model." (PMID 27787621, 2017). "VWF antigen was associated with incident diabetes, but this association was attenuated after adjustment for known risk factors." (PMID 27787621, 2017). "ADAMTS13 activity was associated with an increased risk of incident diabetes (HR 1.17 [95% CI 1.08, 1.27]) after adjustment for known risk factors and VWF antigen levels." (PMID 27787621, 2017). "In the Framingham Heart Study, however, VWF remained significantly associated with incident diabetes after adjustment for a wide range of potential confounders, including insulin resistance." (PMID 27787621, 2017). "High vWF have generally been associated with diabetes, but the results for ADAMTS13 are more diverging." (PMID 29200971, 2017). "The association of ADAMTS13 activity with incident diabetes was strongest in the fourth quartile of VWF antigen level (HR 1.49 [95% CI 1.27, 1.75])." (PMID 27787621, 2017). "Cox proportional hazards models were used to examine the association of ADAMTS13 activity and VWF antigen with incident diabetes." (PMID 27787621, 2017). "VWF has been associated with incident diabetes in a range of studies, but in general the association weakened after adjustment for confounders and became non-significant." (PMID 27787621, 2017). "The VWF antigen level was also associated with an increased risk of diabetes, but this association was attenuated after adjustment for known risk factors." (PMID 27787621, 2017). "Increased levels of von Willebrand factor, an indication of damage to endothelial cells, have been showed association with diabetes." (PMID 28346466, 2017). "On multivariable linear regression, adjusted for age, sex, hypertension, smoking and diabetes, reduced von Willebrand factor was associated with increased basal ganglia perivascular spaces count (r = −.025, P = .032)." (PMID 27576214, 2016). "Eleven ST3GAL4 SNPs were significantly associated with the plasma level of VWF antigen before adjustments for age, BMI, hypertension, diabetes, ever-smoking status, and ABO." (PMID 27584569, 2016). "Only one vascular marker (von Willebrand factor, known to be increased in diabetes) was linked to a retinal vessel response — that of venous maximum constriction." (PMID 27436082, 2016).